MET (MET proto-oncogene, receptor tyrosine kinase)
Diseases named in the same sentence as MET in open-access papers (continued):
Sharing a sentence is not in itself a finding about the gene and the disease.
mucosal melanoma (2 papers, 2020 to 2023). A melanoma that arises from a mucosal site. "Our findings indicate a potential therapeutic strategy based on EGFR and MET inhibitors in mucosal melanoma, which should be further evaluated in vivo and in clinical experiments." (PMID 37679999, 2023). "In summary, our preliminary study highlights the possibility for future in vivo and clinical verification of the utility of MET and EGFR inhibitors as a potential therapeutic strategies in mucosal melanoma." (PMID 37679999, 2023).
non-small cell lung adenocarcinoma (2 papers, 2021 to 2025). Type of epithelial lung cancer arising from glandular origin. "Similarly, MET knock down sensitized two cetuximab resistant non-small cell lung adenocarcinoma cell lines, LXFA 526 L and LXFA 1647 L, to EGFR inhibition." (PMID 33596979, 2021). "For example, in non-small cell lung adenocarcinoma (NSCLC), c-MET overexpression is observed in approximately 20%–25% of clinical cases." (PMID 40520181, 2025).
oropharyngeal squamous cell carcinoma (2 papers, 2014 to 2016). "Identification of MET genetic alteration, mutation, or amplification in oropharyngeal squamous cell carcinoma (OPSCC) could lead to development of MET selective kinase inhibitors." (PMID 24465403, 2014).
ovarian serous adenocarcinoma (2 papers, 2016 to 2022). An adenocarcinoma that arises from the ovary and is characterized by the presence of malignant epithelial cells that, in well differentiated tumors, resemble the epithelium of the fallopian tube or, in poorly differentiated tumors, show anaplastic features and marked nuclear atypia. "However, since most tumor specimens and tumor cell lines used in these prior studies have been ovarian serous adenocarcinoma, data analyzing the role of c-MET in OCCC have been limited." (PMID 27917934, 2016). "The inhibition of c-MET using the non-specific pan-kinase inhibitor crizotinib or the MET-specific HS-10,241 abolishes Tyr907 phosphorylation, sensitizing to PARPi in in vitro and xenograft models of TNBC, NSCLC, and high-grade serous ovarian cancer (HGSOC), independent of BRCA status." (PMID 35681619, 2022).
papilloma (2 papers, 2019 to 2023). A benign epithelial neoplasm that projects above the surrounding epithelial surface and consists of villous or arborescent outgrowths of fibrovascular stroma. "We measured HGF and p-MET expression in papillomas and SCCs from WT and Tpl2−/− mice." (PMID 30631034, 2019).
penile cancer (2 papers, 2022). A primary or metastatic malignant neoplasm that affects the penis. "Therefore, c-MET blockade warrants further investigation in the setting of metastasized penile cancer." (PMID 35406455, 2022). "Our study may pave the way for the translation of MET targeted MFGI and spectroscopy for the intraoperative visualization of other tumors with MET overexpression, such as head and neck, colon, breast, pancreatic, and penile cancer." (PMID 35389070, 2022). "Whereas the lack of biomarkers in penile cancer (PeCa) impedes the development of efficacious treatment protocols, preliminary evidence suggests that c-MET and associated signaling elements may be dysregulated in this disorder." (PMID 35406455, 2022).
Peripheral edema (2 papers, 2021 to 2023). An abnormal accumulation of interstitial fluid in the soft tissues of the limbs. "Peripheral oedema, which is considered a class effect of MET inhibitors, was common but considered manageable and did not lead to permanent treatment discontinuation in any Japanese patients." (PMID 34037224, 2021).
pleural mesothelioma (2 papers, 2019 to 2023). A neoplasm that arises from the mesothelial cells of the pleura. "Overall, our findings are in agreement with evidence obtained in pleural mesothelioma cell lines that displayed co-activation of EGFR, Axl, and MET, supporting the hypothesis of a higher responsiveness to combined targeted therapies." (PMID 31752449, 2019).
preeclampsia (2 papers, 2017 to 2023). Preeclampsia is a hypertensive disorder of pregnancy that is characterized by new-onset hypertension with proteinuria presenting after 20 weeks of gestation, and depending on mild or severe forms may initially present with severe headache, visual disturbances, and hyperreflexia. "The MESH terms preeclampsia, kinases, phosphatases, angiopoietins, soluble tyrosine protein kinase receptor (sTIE2), and cellular-mesenchymal-epithelial transition factor (c-MET) were combined to find relevant articles in the PubMed, PROSPERO, and Cochrane databases." (PMID 37629025, 2023). "We identified serum CK, sTIE2, and c-MET as potentially relevant biomarkers for preeclampsia." (PMID 37629025, 2023).
Renal cyst (2 papers, 2017 to 2025). A fluid filled sac in the kidney. "The ligand to c-MET, hepatocyte growth factor (HGF) is thought to mediate human renal cyst formation." (PMID 28209203, 2017).
serous ovarian carcinomas (2 papers, 2015 to 2022). "This agrees also with the recent report that increased MET protein expression was found in primary cultures of PARPi resistant high-grade serous ovarian carcinomas." (PMID 35628590, 2022).
Skin rash (2 papers, 2016 to 2017). A red eruption of the skin. "A four-genes model (rs884225 in EGFR 3′UTR, rs7787082 in ABCB1 intron, rs38845 in MET intron and rs3803300 in AKT1 5′UTR) was associated with TKIs induced ADRs and skin rash." (PMID 26988277, 2016). "This compensation of EGFR inhibition by HGF/MET signaling might also happen in skin cells and could explain why higher plasma concentrations of HGF correlate with less severe EGFRI-induced skin rash." (PMID 28456787, 2017).
spindle cell neoplasm (2 papers, 2023 to 2025). A benign or malignant neoplasm characterized by the presence of neoplastic spindle cells. "Undifferentiated spindle cell neoplasms with NTRK-rearrangement (or activating mutations in RAF1, BRAF, RET, MET, and others) are rare, recently described lesions in children." (PMID 40491214, 2025). "ES-RMS with TFCP2 rearrangement is a rare malignant tumor and easily confused with other epithelioid or spindle cell tumors, it may harbor additional gene alteration in addition to TFCP2 rearrangement, such as MET mutation, increased copy numbers of EWSR1 and ROS1 gene, high TMB." (PMID 36998041, 2023).
type 2 diabetes (2 papers, 2016 to 2023). "The study provided further insight into the roles of NSO alone or in combination with MET or GLI in type II diabetes mellitus." (PMID 27579151, 2016).
uterine cancer (2 papers, 2019 to 2021). Primary or metastatic malignant neoplasm involving the uterine corpus and/or the cervix. "Indeed, we also detected a MET copy-number gain in one patient (CER3) and EGFR copy-number gains in 2 patients (CER2 and CER3), both of which could be targets for novel molecular treatments for uterine cancer." (PMID 31320709, 2019).
venous thromboembolism (2 papers, 2014 to 2022). Occlusion of the lumen of a vein by a thrombus that has migrated from a distal site via the blood stream. "Somatic tumor mutations in STK11, KRAS, CTNNB1, KEAP1, CDKN2B and MET, which were reported to be associated with cancer-induced venous thromboembolism in an independent study, were infrequent in OSCC." (PMID 35053621, 2022). "Interestingly, an increased incidence of venous thromboembolism has also been observed in the setting of HGF/MET inhibition possibly supporting the notion that anti-HGF/MET drugs can disrupt the functioning of the vascular endothelium." (PMID 24930887, 2014).
alcohol (1 paper, 2016). "The purpose of this study was to determine the importance of Hepatocyte Growth Factor Receptor/MET signaling as an intrinsic repair mechanism for acinar cells following acute damage and chronic alcohol-associated injury." (PMID 27798657, 2016).
arteriovenous malformations (1 paper, 2022). "PIK3CA variants were found in 67% of Klippel Trenaunay Syndrome individuals; KRAS variants in 60% of arteriovenous malformations; MET was mutated in 75% of lymphovenous malformations." (PMID 35807022, 2022).
arthrogryposis (1 paper, 2019). A rare, non-progressive congenital disorder characterized by multiple joint contractures which are present at birth. "By using whole‐exome sequencing, we confirmed MET p.Y1234C mutation to be responsible for arthrogryposis in this pedigree." (PMID 30777867, 2019). "Overall, our study shows MET to be a causative gene of arthrogryposis and MET mutation could cause skeletal muscle dysplasia in human beings." (PMID 30777867, 2019).
atrial fibrillation (1 paper, 2024). A disorder characterized by an electrocardiographic finding of a supraventricular arrhythmia characterized by the replacement of consistent P waves by rapid oscillations or fibrillatory waves that vary in size, shape and timing and are accompanied by an irregular ventricular response. "In this study, we speculate that MET may also be a target gene of miR-1 in atrial fibrillation." (PMID 39221422, 2024).
benign meningioma (1 paper, 2021). A grade I, slowly growing meningioma. "It was found that HGF and c-MET were significantly upregulated in malignant meningioma compared with benign meningioma." (PMID 34408780, 2021).
benign prostate hyperplasia (1 paper, 2023). "Immunohistochemical staining of normal and malignant human prostate samples showed that MET protein expression is absent in epithelial cells of normal prostate glands and low in benign prostate hyperplasia, whereas it is frequently detected in PIN, localized and metastatic prostate tumors." (PMID 37668356, 2023).
bone tumors (1 paper, 2023). "Amplification of MET and MYC genes were negatively correlated with clinical prognosis in bone tumors (p<0.01)." (PMID 37546405, 2023).
bronchioalveolar carcinoma (1 paper, 2011). "Both primary and metastatic bronchioalveolar carcinoma cell lines H358 and H1650 showed a moderate activation of the HER1 and HER2 pathways, with H358 also exhibited a moderate activation of the c-MET and IGF-1R pathways." (PMID 22091388, 2011).
cervical adenocarcinoma (1 paper, 2017). An adenocarcinoma arising from the cervical epithelium. "In this study, we examined the expression of receptor tyrosine kinases, EGFR, HER2 and c-MET, in cervical adenocarcinomas to determine whether they are useful as prognostic factors and therapeutic targets of cervical cancers, with focus on the importance of co-expression of multiple RTKs." (PMID 28859123, 2017).
chronic skin ulcers (1 paper, 2018). "However, because proteolytic degradation of HGF impairs re-epithelialization in chronic skin ulcer patients and restricted the therapeutic effects of HGF, non-native MET-agonists containing macrocyclic peptides have an advantage in treating chronic skin ulcers." (PMID 30322054, 2018).
classical Hodgkin lymphoma (1 paper, 2016). "In classical Hodgkin lymphoma (cHL), the expression of c-MET was detected in the tumor cells from 38 to 52% of the patients, and the expression of HGF was found in 8% of the patients." (PMID 27923392, 2016).
co-infection (1 paper, 2026). "In H1650 cells, all c-MET/EGFR-dual-targeting approaches, i.e., co-infection, co-expression, or expression of the trispecific Db-TriTE, were superior to mono-targeting of EGFR and c-MET." (PMID 41552759, 2026).
cutaneous squamous cell carcinoma (1 paper, 2019). "In summary targeting MET may be a potential new strategy to combat cutaneous squamous cell carcinomas that result from dysregulation in MAPK signaling." (PMID 30631034, 2019).
cyst (1 paper, 2017). A sac-like closed membranous structure that may be empty or contain fluid or amorphous material. "Thus it would be paradoxical that inhibition of c-MET by crizotinib would drive cyst formation unless an unidentified feedback mechanism increased levels of HGF to drive cyst formation via another target." (PMID 28209203, 2017).
developmental verbal dyspraxia (1 paper, 2020). "Mutations in MET are a risk factor for ASD, and MET is also regulated by the transcription factor FOXP2, which causes developmental verbal dyspraxia when mutated." (PMID 36794006, 2020).
diffuse midline glioma (1 paper, 2023). A diffuse glioma that arises from the midline structures of the central nervous system. "In diffuse midline glioma, H3 K27-altered, MET alterations including amplification and activating point mutations have been reported to occur sporadically (8.6–15.0%)." (PMID 37214395, 2023).
edema (1 paper, 2022). An abnormal accumulation of fluid beneath the skin, or in one or more cavities of the body. "As peripheral edema is a class effect, switching to a different MET inhibitor is unlikely to be helpful." (PMID 35466070, 2022).
encephalitis (1 paper, 2025). An acute inflammatory process affecting the brain parenchyma. "Our results indicate that, comparedto the non-encephalitis group, the encephalitis group shows significant upregulationof immune-related genes MET and KIT, while IL1R2 is downregulated." (PMID 40985687, 2025). "The resultsrevealed upregulation of the MET proto-oncogene receptor tyrosine kinase (MET)and KIT proto-oncogene receptor tyrosine kinase (KIT) in the encephalitis group,while interleukin 1 receptor type 2 (IL1R2) was downregulated compared to thenon-SAE group." (PMID 40985687, 2025). "Specifically, we identified six differentiallyexpressed immune genes—MET, KIT, IL1R2, MAFF, CD69, andCEBPD—between the encephalitis and non-encephalitis groups." (PMID 40985687, 2025).
endometrial tumors (1 paper, 2021). "Second, MET mutation promotes the growth and invasion of endometrial tumors both in vivo and in vitro." (PMID 34439385, 2021).
Fulminant hepatitis (1 paper, 2020). Acute hepatitis complicated by acute liver failure with hepatic encephalopathy occurring less than 8 weeks after the onset of jaundice. "In a mouse model of fulminant hepatitis, the intravenous administration of a MET-agonistic DNA aptamer increased the MET activation and suppressed the cell death of hepatocytes in the liver." (PMID 33121208, 2020).
gastric adenoma (1 paper, 2014). A neoplastic polyp that arises from the stomach. "MET inhibition was also observed to enhance autophagy in gastric adenoma cells." (PMID 25221930, 2014).
germ cell neoplasm (1 paper, 1991). "In comparison with normal DNA, tumour DNA of a total of eight patients (seven with germ cell neoplasm and one with testicular lymphoma) showed increased dosages of KRAS2, PDGFA, EGFR, MET and PDGFB." (PMID 1829952, 1991).
giant cell carcinoma (1 paper, 2017). "Somatic MET mutations were almost always found in tumors without epithelial components, i.e., in three patients with giant cell carcinoma, yet only in one with pleomorphic carcinoma." (PMID 28418914, 2017).
Gynecomastia (1 paper, 2013). Abnormal development of large mammary glands in males resulting in breast enlargement. "We found that expression patterns in gynecomastia were largely comparable with normal female breast tissue; i.e. no expression of HER2, EGFR, MET, GLUT1 and CAIX detectable." (PMID 23308200, 2013).
hereditary cancer syndrome (1 paper, 2024). "Among patients with MPRT and a diagnosed hereditary cancer syndrome, multiple CRCC was reported in patients with VHL disease (93.5% (43/46)) and constitutional chromosome 3 translocations (100% (5/5) and multiple PRCC in those with germline MET protooncogene mutations (95.2% (20/21))." (PMID 38802529, 2024).
hereditary nonpolyposis colorectal cancer (1 paper, 2005). "In a human hereditary nonpolyposis colorectal cancer (HNPCC)-derived cell line (HCA-7), we observed a high level of MET expression." (PMID 15785735, 2005).
histiocytic sarcoma (1 paper, 2019). An aggressive malignant neoplasm with a poor response to therapy, usually presenting as stage III/IV disease. "Although the clinical efficacy of MET inhibitor for the case is not known, clinical benefit from a rare thoracic histiocytic sarcoma patient receiving crizotinib was reported previously." (PMID 31369639, 2019).
hypersensitivity pneumonitis (1 paper, 2024). Hypersensitivity pneumonitis (HP) is a pulmonary disease with symptoms of dyspnea and cough resulting from the inhalation of an antigen to which the subject has been previously sensitized. "Macrophage c-MET expression was increased in non-hypersensitivity pneumonitis conditions, including IPF and CTD-ILD, while neutrophil c-MET expression levels were higher in IPF patients compared to fibrotic HP and CTD-ILD, with no expression detected in non-fibrotic HP." (PMID 38909206, 2024).
inherited cancer syndromes (1 paper, 2024). "In addition, because MET belongs to the same family (the receptor tyrosine kinase family) as RET, a proto-oncogene already known to be mutated in other inherited cancer syndromes, the MET proto-oncogene was sequenced rather than the two other genes also found at this locus." (PMID 38652103, 2024).
leishmaniasis (1 paper, 2022). Infectious disease that is transmitted through the bite of hematophagous female phlebotomine sand flies. "Here, we investigated the importance of c-MET expression on neutrophils in their recruitment to the infection site and the role of c-Met expression in the pathology of leishmaniasis." (PMID 35041723, 2022).
lung abscess (1 paper, 2024). A bacterial, fungal or parasitic abscess that develops in the lung parenchyma. "Herein, we report a case of G‐CSF‐producing lung adenocarcinoma positive for MET exon 14 skipping mutation mimicking lung abscess." (PMID 38919814, 2024).
lung sarcoma (1 paper, 2024). A malignant mesenchymal neoplasm that arises from the lung. "Savolitinib is a MET-TKI approved in China for the treatment of metastatic NSCLC with MET exon 14 skipping changes that progress after platinum-based chemotherapy or cannot tolerate platinum-based chemotherapy, based on the results of a pivotal phase II trial in NSCLC/lung sarcoma-like carcinoma." (PMID 38181277, 2024).
Lymphatic Metastasis (1 paper, 2023). Transfer of a neoplasm from its primary site to lymph nodes or to distant parts of the body by way of the lymphatic system. "The expression of the MET and ICAM1 in the lymphatic metastasis group were significantly higher than that in the non-metastatic group and the normal group (P<0.001)." (PMID 37274228, 2023).
Maffucci syndrome (1 paper, 2019). Maffucci syndrome is a very rare genetic bone and skin disorder characterized by multiple enchondromas, leading to bone deformities, combined with multiple dark, irregularly shaped hemangiomas or less commonly lymphangiomas. "In a genetic study of various breast lesions, mutated tubular adenomas showed primarily mutations in MET and FGFR3, whereas enchondromas in Maffucci’s syndrome have been known to harbour isocitrate dehydrogenase (IDH1 and 2) mutations." (PMID 31585326, 2019).
malignant meningiomas (1 paper, 2021). "HGF and c-MET were found to be positively expressed in both benign and malignant meningiomas and were both localized in the cell membrane and cytoplasm." (PMID 34408780, 2021). "The c-MET inhibitor (SU11274) and the PI3K inhibitor (LY294002) suppressed HGF-induced migration, invasion, and EMT of human malignant meningioma cells." (PMID 34408780, 2021).
MALT lymphoma (1 paper, 2016). An indolent, extranodal type of non-Hodgkin lymphoma composed of small B-lymphocytes (centrocyte-like cells). "c-MET inhibition suppressed the hepatic and pulmonary MALT lymphoma, while the gastric MALT lymphoma showed only a tendency to decrease in size." (PMID 27923392, 2016). "c-MET was found in the lymphocytes composing mucosa-associated lymphoid tissue (MALT) lymphoma, and HGF was recognized mostly in the endothelial cells and macrophages in the MALT lymphoma." (PMID 27923392, 2016).
meningeal cancer (1 paper, 2023). "However, it remains unclear whether CDKN2A abnormalities and MET amplification are involved in the process of brain metastasis of LUAD and how it affects the prognosis of meningeal cancer patients." (PMID 36937524, 2023).